NF1 (neurofibromin 1)
Diseases named in the same sentence as NF1 in open-access papers (continued):
Sharing a sentence is not in itself a finding about the gene and the disease.
neurofibromatosis type 1 (continued). "Neurofibromatosis type 1 (NF1) is a neurocutanous-skeletal syndrome caused by mutations in the NF1 tumor suppressor gene located at 17q11.2." (PMID 30092804, 2018). "Germline mutations in NF1 are associated with neurofibromatosis type 1 an autosomal dominantly inherited tumor predisposition syndrome." (PMID 30345349, 2018). "Cutaneous neurofibromas (cNF) are a nearly ubiquitous symptom of neurofibromatosis type 1 (NF1), a disorder with a broad phenotypic spectrum caused by germline mutation of the neurofibromatosis type 1 tumour suppressor gene (NF1)." (PMID 29695767, 2018). "NF1, a tumor-suppressor gene in which mutations cause the hereditary cancer predisposition disease, neurofibromatosis type 1, encodes a negative regulator of RAS proteins." (PMID 30018380, 2018). "Mutations of the NF1 gene give rise to neurofibromatosis type 1 (NF1), also known as von Recklinghausen disease." (PMID 29666462, 2018). "Of note, one of the cerebellar GBMs occurred in a patient with a NF1 germline mutation (Neurofibromatosis type 1)." (PMID 30333046, 2018). "NF1 (neurofibromin 1), associated with neurofibromatosis type 1, has been linked to cognitive impairments, differed in the patients with and without hallucinations." (PMID 30367354, 2018). "Neurofibromatosis type 1 is a disease caused by mutation of neurofibromin 1 (NF1), loss of which results in hyperactive Ras signaling and a concomitant increase in cell proliferation and survival." (PMID 29662612, 2018). "In the germline, one NF1 loss‐of‐function allele causes the Mendelian disorder neurofibromatosis type 1." (PMID 30573688, 2018). "In monogenic dominantly inherited diseases such as Neurofibromatosis type 1 (NF1), a loss of function mutation in one NF1 allele leads to a reduced amount of the functional corresponding protein in all body cells expressing this gene." (PMID 29670214, 2018). "Neurofibromatosis type 1, caused by constitutional inactivating mutations in the tumour suppressor gene NF1, is a neurodegenerative disorder predisposing individuals to both benign and malignant tumours." (PMID 28637487, 2017). "Neurofibromatosis type 1 is an autosomal-dominant disorder caused by a mutation in a tumor suppressor gene encoding the protein neurofibromin 1 (NF1), affecting 1 in 3,500 individuals worldwide." (PMID 29354122, 2017). "Correspondingly, germline mutations in NF1, which cause neurofibromatosis type I, often display autistic-like behaviors." (PMID 28321286, 2017). "Neurofibromatosis type 1 (NF1) is an autosomal dominant genetic disorder caused due to the loss and/or mutation of NF1 tumor suppressor gene." (PMID 29212209, 2017). "Neurofibromatosis type I is a model genetic disorder due to the high mutation rate of its causative gene, NF1." (PMID 28961165, 2017). "Haploinsufficiency-derived UTP6 under-expression in neurofibromatosis type 1 (NF1) cells resulted in those cells being less susceptible to apoptosis." (PMID 28589857, 2017). "Mutations in the NF1 gene are associated with neurofibromatosis type I and Watson syndrome, a variant of NF1." (PMID 28116311, 2017). "Mutations in NF1 are linked to neurofibromatosis type 1, juvenile myelomonocytic leukemia and Watson syndrome." (PMID 29354122, 2017). "Approximately 10–15% of pediatric JMML occur in association with neurofibromatosis type I, disease resulting from mutations in the neurofibromatosis type I gene (NF1) that encodes neurofibromin." (PMID 28955657, 2017). "Neurofibromas are slow growing, poorly vascularized soft tissue masses and are a hallmark of the autosomal dominant genetic disorder, neurofibromatosis type 1 (NF-1)." (PMID 29147633, 2017). "Neurofibromatosis type 1 is a disease caused by mutations in the NF1 gene, a negative regulator of the Ras signaling pathway." (PMID 29354122, 2017). "A clear example is neurofibromatosis type 1, in which about 7% of mutations in the NF1 gene are due to total gene deletions or intragenic CNAs28." (PMID 28051113, 2017).
neurofibromatosis type 1 (continued). "Neurofibromatosis type 1 (NF1) is a hereditary tumor syndrome caused by mutations of the NF1 gene and resulting dysregulation of the Ras-pathway." (PMID 27448806, 2016). "Haploinsufficiency of the NF1 gene, which also codes for a RasGAP, causes neurofibromatosis type 1, a complex neuro-cutaneous condition that is associated with cognitive impairment and autism spectrum disorders." (PMID 27827368, 2016). "Nf1 mutations or deletions are suggested to underlie the tumor predisposition of NF1 (neurofibromatosis type 1) and few treatments are available for treating NF1 patients with advanced malignant tumors." (PMID 27741517, 2016). "Deletion of neurofibromin 1 (Nf1), a gene mutated in neurofibromatosis type 1, was found to direct ectopic oligodendrogenesis from SGZ-NSCs." (PMID 27854261, 2016). "NF-1, also called von Recklinghausen's disease, is an autosomal dominant genetic disorder linked to chromosome 17 and presents with neural tumors, cutaneous pigmentations, and Lisch nodules." (PMID 27867667, 2016). "Studies showed that JQ1 or BRD4 knockdown in NF1 (Neurofibromatosis type 1)-associated malignant peripheral nerve sheath tumors decreased the expression of CCND1." (PMID 26830473, 2016). "For instance, neurofibromatosis type I is caused by mutations in the neurofibromin 1 gene (NF1), and in 50% of the patients the identified mutations result in splicing alterations." (PMID 26116573, 2015). "NF-1 (von Recklinghausen's disease) has been associated with an increased incidence of MPNSTs and MTTs." (PMID 26114002, 2015). "Neurofibromatosis type I (NF1) is a multi-system disease caused by loss-of-function mutations in the NF1 gene which encodes a Ras-GAP protein, Neurofibromin." (PMID 25775093, 2015). "Neurofibromatosis type 1 (NF1) is an autosomal dominant disease caused by mutations in the NF1 gene, mapped at chromosome 17q11.2, which produces an ubiquitous protein called neurofibromin." (PMID 26161090, 2015). "Mutations in Nf1 are the causes of the common neurological disorder Neurofibromatosis type 1 (NF1), which affects 1 in 3,000 live births." (PMID 26536237, 2015). "We analysed a female patient diagnosed with neurofibromatosis type 1 (NF1) and carrying the heterozygous NF1 mutation NM_000267:c.405delG p.E8Nfs*16." (PMID 25775093, 2015). "Neurofibromatosis type 1 (NF1), also called von Recklinghausen's disease, is a multisystemic disease caused by an alteration of the NF1 gene, a tumor suppressor located on the long arm of chromosome 17 (17q11.2)." (PMID 26442164, 2015). "In neurofibromatosis type 1 (NF1), the NF1 gene contains mutations that alter functioning of this protein." (PMID 26089803, 2015). "Inactivating mutations in the NF1 gene leads to neurofibromatosis type 1, a type of tumor of the nervous system." (PMID 26167953, 2015). "Neurofibromatosis type 1 (NF1) is a common autosomal dominant genetic disorder caused by mutations in the NF1 gene." (PMID 24789688, 2014). "Neurofibromatosis is a rare disease that includes two variants that is divided into neurofibromatosis type 1 (NF1) and type 2 (NF2)." (PMID 25478247, 2014). "IRA2 is a yeast ortholog of the human tumor suppressor gene NF1, mutations in which cause the disease neurofibromatosis type I (NF1)." (PMID 24386979, 2014). "Our study suggested that PKC α and β were crucial for supporting hyperactive Ras signaling under Nf1 deficient condition and potential targets for therapeutic intervention of neurofibromatosis type 1, especially MPNST." (PMID 25301738, 2014). "Neurofibromatosis type 1 (NF1) is an autosomal dominant disease caused by loss of function mutations in the NF1 gene, which encodes the Ras-GAP protein neurofibromin." (PMID 24465906, 2014). "Neurofibromatosis type 1, also known as NF1 or von Recklinghausen's disease, is a tumour predisposition syndrome characterized by the development of multiple neurofibromas, café-au-lait spots and Lisch nodules." (PMID 25026295, 2014).
neurofibromatosis type 1 (continued). "Nf1 which is a negative regulator of the ras signal transduction pathway, mutated in neurofibromatosis type 1, also confers an increased risk of developing WT GISTs." (PMID 23593401, 2013). "In humans, inherited heterozygous mutations in NF1 cause neurofibromatosis type 1, which is characterized by skin hyper-pigmentation and Schwann cell based tumors." (PMID 23555837, 2013). "Genetic syndromes of pheochromocytoma include multiple endocrine neoplasia type 2 (MEN2A and 2B), neurofibromatosis type 1 (NF1), the pheochromocytoma-paraganglioma syndrome (mutation of the SDHB or SDHD genes), and von Hippel-Lindau syndrome (VHL)." (PMID 23401807, 2013). "Neurofibromatosis type 1 (Von Recklinghausen disease) is caused by a mutation in the gene responsible for the production of neurofibromin 1, which is involved in cell signalling." (PMID 23984157, 2013). "Recently, 23 human MPNSTs in patients with inherited neurofibromatosis type 1 (NF1; heterozygous germline NF1 mutation) were examined using high resolution aCGH." (PMID 24009526, 2013). "Neurofibromatosis type 1 (NF1), a neuroectodermal disorder, is caused by germline mutations in the NF1 gene." (PMID 23947441, 2013). "Mutations of the neurofibromin 1 gene cause neurofibromatosis type 1, a disease in which learning and behavioral abnormalities are common." (PMID 23056445, 2012). "Germline loss-of-function mutations of NF1 lead to neurofibromatosis type 1, a dominant autosomal genetic disorder clinically characterized by neurofibromas, cafe-au-lait spots, and a high risk to develop juvenile myelomonocytic leukemia (JMML)." (PMID 23077663, 2012). "Mutations in the NF1 gene cause Neurofibromatosis type 1, an autosomal dominant disease that affects approximately 1 in 3000 individuals, making it one of the most common inherited genetic disorders." (PMID 23145129, 2012). "Neurofibromatosis type 1 (NF1) is a genetic disorder resulting from mutations in the NF1 tumour suppressor gene." (PMID 21726432, 2011). "Mutations in the NF1 gene cause Neurofibromatosis 1 which is mainly characterized by the development of multiple benign tumors of nerves and skin." (PMID 22096509, 2011). "These cases suggest that the events involved in the transformation of benign plexiform neurofibromas to MPNSTs in Neurofibromatosis type 1, follow a spatiotemporally programme that is influenced by heritable factors other than NF1 mutations." (PMID 20687928, 2010). "Neurofibromatosis type 1 (NF1) is an autosomal dominantly inherited neurocutaneous disorder due to mutations in NF1 on 17q11.2." (PMID 19333415, 2009). "Specific NF1 variants are associated with mild clinical manifestations of neurofibromatosis type 1; for instance, variants affecting Arg1809 tend to show café-au-lait macules and Noonan-like dysmorphic features but do not have neurofibromas and some other typical neurofibromatosis features." (PMID 41443197, 2026). "In addition, germline heterozygous loss-of-function mutations in NF1 cause neurofibromatosis type 1." (PMID 39804140, 2025). "Additionally, radiation therapy is generally avoided in patients with neurofibromatosis type 1 (NF–1) because of the increased risk of secondary malignancies." (PMID 40867225, 2025). "While 80%–84% of CPT cases present with neurofibromatosis type 1, caused by the variations in the NF1 gene, the underlying cause of CPT remains unclear." (PMID 40462134, 2025). "Similarly, NF1 gene mutations are commonly seen in neurofibromatosis type 1-associated GISTs and are characterized by a distinct molecular profile lacking KIT or PDGFRA mutations." (PMID 40282558, 2025). "However, studies have recently been conducted on neurofibromin, a protein encoded by the NF1 gene responsible, if mutated, for neurofibromatosis type 1, which demonstrate its direct involvement in the regulation of the circadian rhythm." (PMID 40299482, 2025).
neurofibromatosis type 1 (continued). "We performed a postmortem study of three children aged <10 years old with high-grade midline gliomas—two (PD50297 and PD51123) with sporadic tumors (H3F3A K27M mutant) and one with neurofibromatosis type 1 with a pathogenic truncating NF1 (c.3113 + 1G>A) germline mutation." (PMID 40000831, 2025). "NF1 (neurofibromatosis type 1) forms the most common type of this disorder, with an estimated incidence of 1:3000 live births worldwide and is caused by heterozygous loss-of-function variants of the NF1 gene at 17q11.2." (PMID 38448973, 2024). "Neurofibromatosis type 1 (NF1) is an autosomal dominant genetic disorder characterized by the predisposition to develop tumors such as malignant peripheral nerve sheath tumors (MPNSTs) which represents the primary cause of death for NF1-affected patients." (PMID 39409151, 2024). "Neurofibromatosis type 1 (NF1) is caused by mutations in the NF1 gene." (PMID 38339230, 2024). "Neurofibromatosis type 1 (NF1) is a neurocutaneous autosomal dominant disorder, with a birth incidence of 1:3500, caused by a heterozygous inactivating mutation in the tumor suppressor NF1 gene (17q11.2)." (PMID 39409151, 2024). "Neurofibromatosis type 1 is associated with a mutation in the large NF1 gene." (PMID 38893137, 2024). "Neurofibromatosis type 1 (NF type 1) is an autosomal dominant disease with typical clinical manifestations, such as skin lesions, Lisch nodules, optic pathway gliomas, and neurofibromas, caused by the mutation of the NF1 gene." (PMID 39105060, 2024). "Type 1 neurofibromatosis (NF1) is an autosomal dominant inherited condition that causes a tumour predisposition due to inactivating mutations in NF1, a tumour suppressor gene which encodes the RAS inhibitor neurofibromin involved in the regulation of cell growth and survival." (PMID 38893021, 2024). "Prior studies suggest that as many as 30% of neurofibromatosis type 1-associated missense mutations in NF1 result in aberrant pre-mRNA splicing which may explain the observed loss of NF1 protein in these specimens." (PMID 39472976, 2024). "Malignant transformation can occur either sporadically or in patients with the tumor-predisposing genetic syndrome Neurofibromatosis type 1 (NF1), caused by loss of function mutations in the tumor suppressor NF1 gene encoding the Ras-GTPase activating protein (Ras-GAP) neurofibromin." (PMID 38995012, 2024). "Neurofibromatosis type 1 results from loss-of-function NF1 pathogenic variants (PVs)." (PMID 37186028, 2023). "Mutations in NF1 gene could cause allelic disorders with clinical spectrum of Neurofibromatosis type 1 to Noonan syndrome." (PMID 36803953, 2023). "Specifically, the cluster of keywords in red (cluster 1,37) associated with the topic “neurofibromatosis type 1” includes the following: “Activation”, “Angiogenesis”, “Growth factor”, “Invasion”, “Mutation”, “Plexiform Neurofibroma”, “NF1 gene”, “Proliferation”, and “Ras”." (PMID 36776342, 2023). "Neurofibromatosis type 1 is an autosomal-dominant condition caused by NF1 gene inactivation." (PMID 37238595, 2023). "Neurofibromatosis type 1 is an uncommon neurogenetic condition characterized by pigmentary abnormalities, learning and social difficulties, and a susceptibility for benign and malignant tumor growth due to NF1 gene germline mutations." (PMID 36090331, 2022). "Neurofibromatosis type 1 is a monogenic disease caused by mutations in the NF1 gene." (PMID 35801779, 2022). "Neurofibromatosis type 1 (NF1) is an autosomal dominant multisystem disorder with tumor predisposition caused by heterozygous pathogenic variants in the neurofibromin gene (NF1, located on chromosome 17q11.2), which encodes for a tumor suppressor protein." (PMID 35119474, 2022).
neurofibromatosis type 1 (continued). "This group is heterogeneous, not typically responsive to imatinib or other typical tyrosine kinase inhibitors (TKI), and includes SDH-deficient tumors (14%), tumors with mutations in NF1 (type 1 neurofibromatosis), BRAF V600E, and NTRK (0.5% each), and other rare mutations." (PMID 35954353, 2022). "Malignant peripheral nerve sheath tumors (MPNSTs) are soft-tissue sarcomas that surround peripheral nerves and occur either sporadically or more often in association with neurofibromatosis type 1 (NF1, von Recklinghausen disease), an inherited disorder caused by germline mutations of the NF1 gene." (PMID 35625983, 2022). "Neurofibromatosis type 1 is a rare neurogenetic syndrome, characterized by pigmentary abnormalities, learning and social deficits, and a predisposition for benign and malignant tumor formation caused by germline mutations in the NF1 gene." (PMID 35188187, 2022). "Both entities are often associated with the genetic disorder neurofibromatosis type 1 (NF-1)." (PMID 35832560, 2022). "Aberrant induction of Ras/MEK/ERK signaling is mandatory for neoplastic growth in Neurofibromatosis type 1 (NF1), a tumor-predisposing genetic disorder caused by loss of function mutations of the NF1 gene encoding the Ras-GAP (GTPase-activating protein) neurofibromin." (PMID 35393510, 2022). "Neurofibromatosis type 1 is an autosomal dominant disease caused by NF1 gene mutation." (PMID 35801779, 2022). "Here, the authors show in mouse models of Neurofibromatosis-1 (NF1) that Nf1 mutations differentially drive both central and peripheral nervous system tumor growth in mice through reduced hyperpolarization-activated cyclic nucleotide-gated (HCN) channel function." (PMID 35589737, 2022). "NF1, one of the RasGAPs encoding neurofibromin, is the causative gene of neurofibromatosis type I. Previous studies have reported learning disabilities in 30–65% of children with neurofibromatosis type I and memory impairment in neurofibromatosis type I model mice." (PMID 36188467, 2022). "The NF1 variant could lead to a frameshift of NF1 and thus a loss-of-function effect, which is associated with neurofibromatosis type I and could explain the cafe-au-lait macules in this patient." (PMID 35346302, 2022). "The NF1 gene is a tumor suppressor gene; therefore, loss of function due to a mutation leads to increase in cell proliferation and results in the development of neurofibromatosis type 1." (PMID 34055682, 2021). "Interestingly, NF2 is genetically unrelated to the more common neurofibromatosis type 1 (NF1) which is due to pathogenic variants of the tumor suppressor NF1 gene on chromosome 17." (PMID 33445724, 2021). "One such publication studied NF1, a gene causing neurofibromatosis type 1." (PMID 34503274, 2021). "In vitro experiments revealed that the three NFFs obtained from three independent neurofibromatosis 1 patients exhibited point mutations of the NF1 gene, which result in reduced NF1 protein expression compared with that in HEFs established from healthy volunteers." (PMID 34011935, 2021). "A novel mutation in NF1 gene was identified and in vitro functional studies were performed, which provided a potential molecular mechanism to explain the bone maldevelopment of patients with neurofibromatosis type 1." (PMID 33764694, 2021). "NF1 is a tumor‐suppressor gene; a mutation in this gene causes neurofibromatosis type 1." (PMID 34605602, 2021). "Neurofibromatosis type 1 (NF1) is caused by loss-of-function variants in the NF1 gene." (PMID 34782607, 2021). "Neurofibromatosis type I is caused by autosomal dominant mutations in the NF1 gene." (PMID 32025336, 2020).